MEG3 (maternally expressed 3)
Diseases named in the same sentence as MEG3 in open-access papers (continued):
Sharing a sentence is not in itself a finding about the gene and the disease.
tumor (continued). "Of these, lnc-DLK1-4 (often called MEG3, a well-characterized tumor suppressor) could be annotated to these two gene sets, supporting the utility of this SOM analysis on initial prediction for potential roles of unknown lncRNAs." (PMID 26918340, 2016). "MEG3 is a non-coding RNA that functions asa tumor suppressor in colon cancer cell lines." (PMID 27508057, 2016). "In addition, a relatively lower level of MEG3 mRNA was measured in tumor tissues treated with GE11-VLPs-MEG3 than in cells in vitro culture." (PMID 26992211, 2016). "This suggests that palbociclib or other CDK4/6 inhibitors could be used therapeutically to target multiple tumor types that rely on MEG3 regulated pathways for growth." (PMID 27832204, 2016). "All of the MEG3 isoforms have been recognized to inhibit tumor cell growth." (PMID 26805815, 2016). "The hypermethylation in the MEG3 promoter region as well as the intergenic germ line-derived differentially methylated region (IG-DMR) would cause proliferation of cancer cells and blood vessels and then accelerate tumor metastasis and malignant." (PMID 26637808, 2016). "Lower level of MEG3 was significantly correlated with advanced tumor stage (p = 0.03)." (PMID 27793008, 2016). "In the meanwhile the VLPs contained an lncRNA MEG3 RNA fragment, which acted as a tumor inhibitor." (PMID 26992211, 2016). "MEG3 is located on chromosome 14q32, a region proposed to contain putative tumor suppressors." (PMID 26934323, 2016). "Strong evidence exists to support that MEG3 is a lncRNA tumor suppressor." (PMID 27148353, 2016). "Given MEG3 is a lncRNA that plays critical roles in tumor cellular proliferation, migration and invasion, SNPs in MEG3 may affect cell phenotypes and cause the risk of developing cancer." (PMID 26934323, 2016). "Similarly, the final tumor mass in the GE11-VLPs-MEG3 group was much less than in the two control groups." (PMID 26992211, 2016). "Likewise, MEG3 downregulation is associated with advanced TNM stages, deeper tumor invasion and inferior OS intervals." (PMID 26064090, 2015). "Our result also showed 2.71 fold decreasing of MEG3 in tumor tissues." (PMID 26159226, 2015). "MEG3 expression is significantly decreased in tumor tissues compared with adjacent normal tissues." (PMID 25559585, 2015). "It was also observed that the upregulation of MEG3 led to the inhibition of tumor growth." (PMID 25992654, 2015). "However, our research showed that MEG3 elevated in HCC tumor tissues and correlated with AFP elevation in human." (PMID 26136615, 2015). "Taken together, these results suggest that MEG3 may act as a tumor suppressor through inhibiting cell proliferation, migration and invasion, and promoting cell apoptosis in GC." (PMID 26253106, 2015). "MEG3 is an imprinted lncRNA which is downregulated in many types of cancers and previously hypothesized to function as a tumor suppressor in a mechanism that is still not well understood." (PMID 25630241, 2015). "Maternally expressed gene 3 (MEG3) is a maternally expressed lncRNA and may function as a tumor suppressor by inhibiting angiogenesis." (PMID 26090403, 2015). "The rank of MEG3 was three, and MEG3 was reported to function as a novel lncRNA tumor suppressor." (PMID 24498199, 2014).
tumor (continued). "Forced expression of MEG3 inhibited the growth of human cancer cell lines such as HeLa, MCF-7, and H4, suggesting that MEG3 may act as a tumor suppressor, while downregulation of MEG3 enhanced autophagy, increased cell proliferation and inhibited cell death." (PMID 25543668, 2014). "Moreover, ectopic expression of MEG3 was found to suppress the growth of several human cancer cell lines, further supporting the role of MEG3 as a tumor suppressor." (PMID 24908062, 2014). "MEG3 has been reported to act as a tumor suppressor in a broader range of cancers." (PMID 25741387, 2014). "qRT-PCR analysis of MEG3 expression was then performed in selected tumor tissues." (PMID 24098911, 2013). "MEG3 was the first lncRNA to be attributed tumor suppressive function." (PMID 24305655, 2013). "GTL2/MEG3 overexpression inhibits tumor cell proliferation in vitro." (PMID 24970160, 2013). "DLK1 is located in the DLK1/MEG3 imprinted locus on human chromosome 14q32.3 and MEG3, coding for a maternally imprinted long noncoding RNA with tumor suppressive function, was also found to be specifically silenced through methylation in NFPAs, but not in other hypophyseal adenoma types." (PMID 23756599, 2013). "Moreover, ectopic expression of MEG3 was found to suppress the growth of several human cancer cell lines, further supporting the effect of MEG3 on tumor suppression." (PMID 24036441, 2013). "Various lines of evidence support a tumor suppressor function for MEG3 lncRNA." (PMID 24006935, 2013). "In conclusion, MEG3 lncRNA can be considered a novel tumor suppressor lncRNA." (PMID 23222637, 2012). "MEG3 lncRNA is expressed in many normal tissues (i.e., human pituitary, including normal gonadotroph cells) but absent in a continuously increasing list of primary human tumors and tumor cell lines." (PMID 23222637, 2012). "Moreover, ectopic expression of MEG3 RNA was found to suppress the growth of several human cancer cell lines, further supporting the role of MEG3 as a tumor suppressor." (PMID 21489289, 2011). "Previous studies have illustrated that MEG3 may affect proliferation and apoptosis of tumor cells." (PMID 41480643, 2026). "Thus, MEG3 and HOTAIR lncRNAs are potential biomarkers for NF-PitNET and could be associated with aggressive tumor behavior." (PMID 40362297, 2025). "Moreover, studies also revealed that MEG3 was downregulated in tumor tissues." (PMID 39124865, 2024). "Interestingly, MEG3 was identified as a tumor suppressor that is a downstream target of cAMP." (PMID 38827318, 2024). "Thus, niraparib mediated-MEG3 upregulation is a crucial mechanism for tumor inhibition." (PMID 38047026, 2023). "Finally, the lncRNA MEG3 has also been found to act as a tumor suppressor in AML." (PMID 37267628, 2023). "Similarly, MEG3 can also act as a ceRNA to regulate tumour cell proliferation and apoptosis." (PMID 36831352, 2023). "Moreover, the level of MEG3 had a partial correlation with the tumour grade." (PMID 37525401, 2023). "Similarly, EVs derived from adipose-tissue-derived MSC (AT-MSC) loaded with the long non-coding RNA maternally expressed gene 3 (lncRNA MEG3) inhibit tumor cell proliferation and tumor growth via a mechanism dependent on PTEN activation and the inhibition of the β-catenin pathway." (PMID 37175226, 2023). "These indicate that MEG3 may be negatively correlated with most tumor progression." (PMID 36033389, 2022). "Therefore, MEG3 has an anti-tumor effect in BCa and could potentially provide alternative treatment options." (PMID 36544907, 2022). "In addition, Zhang and Feng (2017) confirmed that MEG3 might play a tumor-suppressive role in PC by sponging miR-183 and targeting the brain protein I3 (BRI3)." (PMID 36544907, 2022).
tumor (continued). "In addition, upregulation of MEG3 could suppress tumour growth and cell proliferation in gemcitabine-resistant NSCLC by modulating PTEN signalling-mediated cell apoptosis." (PMID 35379783, 2022). "In addition, suppression of HDAC3 also resulted in the upregulation of MEG3, a lncRNA tumor suppressor specifically silenced in NFPAs, as well as components in the Rb signaling pathway such as P16 and E2F1, both of which have been suggested to be involved in the pathogenesis of NFPAs." (PMID 35646715, 2022). "Hence, these studies infer that MEG3 is a tumor suppressor in MM." (PMID 36544907, 2022). "MEG3 exerts its tumor-suppressive effect by regulating various cancer hallmarks, as it could inhibit tumor cell proliferation, induce cell death, reduce invasion and metastasis, prevent angiogenesis, and inhibit tumor cells’ metabolic reprogramming." (PMID 36551518, 2022). "Overexpression of MEG3 may affect and regulate common cancer-related pathways and interact with miRNAs, mRNAs and proteins through transcriptional regulation, post-transcriptional regulation or epigenetic regulation to play a tumor suppressor role." (PMID 36544907, 2022). "Therefore, MEG3 is considered as a potential tumor suppressor." (PMID 36544907, 2022). "Thus the researches postulate that overexpression of MEG-3 could serve the functions of a tumor suppressor by impeding the functions of miR-421." (PMID 36530526, 2022). "MEG3 is significantly downregulated in primary human cancers such as lung cancer, liver cancer, gallbladder cancer, pituitary tumors and different cancer cell lines, and its expression level is significantly related with tumor grade, metastasis and poor prognosis." (PMID 36344947, 2022). "Interestingly, MEG3 levels were significantly increased in the Gsp-mutated group compared to the non-mutated one, and determined a reduction in tumor proliferation and invasiveness." (PMID 34484116, 2021). "We found that MEG3 could inhibit the proliferation and invasion of some kind of tumor cells." (PMID 34238211, 2021). "Thus, our data uncovered a novel mechanism that DDP induced pyroptosis via activation of MEG3/NLRP3/caspase-1/GSDMD pathway in TNBC to exert anti-tumor effects, which may help to develop new strategies for the therapeutic interventions in TNBC." (PMID 34326697, 2021). "In addition, SUC accumulation was a downstream effect of the tumour suppressor lncRNA MEG3." (PMID 31793175, 2020). "Thus, the tumor suppressor function of MEG3 is closely related to the activity of telomerase." (PMID 33256840, 2020). "Furthermore, MEG3 inhibits tumor cell proliferation by blocking the Notch signaling pathway." (PMID 33256840, 2020). "Moreover, MEG3 inhibited tumor metastasis through the mTOR-mediated EMT." (PMID 33061817, 2020). "In addition, overexpression of MEG3 could suppress the migration, invasion, and metastasis of tumor cells by inhibiting the expression of clusterin." (PMID 33520725, 2020). "Furthermore, MEG3 inhibited tumour growth and up‐regulated expression of QKI‐5 in vivo." (PMID 30565858, 2019). "In addition, overexpression of MEG3 lessened significantly xenograft tumor volume and weight." (PMID 29808164, 2018). "In addition to oncogenes, lncRNA act as tumor suppressors such as Meg3, AOC4P, INXS and Dreh." (PMID 30158867, 2018). "Furthermore, tumor xenograft assays confirmed that MEG3 amplification could decrease tumor growth in vivo." (PMID 30282996, 2018).
tumor (continued). "For example, the lncRNA named MEG3 was recently implicated as an influencer of the signal transducer and activator of transcription 3 (STAT3) expression, by altering miR-21 expression in ovarian cancer; it has been shown to function as a tumor suppressor in many cancer types." (PMID 29596364, 2018). "Therefore, we suggest that Meg3 acts as a tumor suppressor in EOC, which may be achieved by initiating autophagy and causing type II cell death." (PMID 28423647, 2017). "Furthermore, we confirmed that the level of MEG3 methylation was significantly decreased in postoperative plasma, implying that MEG3 hypermethylation in plasma might be a result of the tumor tissue." (PMID 28740189, 2017). "However, one should keep in mind that the MEG3 tumor suppressive function is also EZH2-mediated." (PMID 26992233, 2016). "Therefore, lncRNA MEG3 was determined as a novel tumor suppressor in human GC." (PMID 26253106, 2015). "MEG3 may inhibit tumor progression by inhibiting angiogenesis." (PMID 26090403, 2015). "Therefore, Meg3 is supposed to have tumor suppressor properties." (PMID 25005035, 2014). "Furthermore, correlation analysis of MEG3 expression with clinical pathological features of NSCLC patients, revealed a significant association between MEG3 downregulation and advanced pathological stage (I/II,37; IIIa/b,IV,7) and NSCLC tumor size." (PMID 24098911, 2013). "Conversely, tumor-suppressor lncRNAs, such as GAS5 and MEG3, can inhibit ERK activity, restoring apoptotic sensitivity." (PMID 41020820, 2025). "Conversely, downregulated lncRNAs like NEAT1, MEG3, and PRINS normally function as tumor suppressor molecules that maintain epidermal homeostasis through pro-apoptotic and anti-inflammatory mechanisms." (PMID 40981386, 2025). "The downregulation of several lncRNA with tumour suppressor activity such as BGL3, GAS5, MEG3, NBAT-1 and PTENP1 have been reported in different cancers." (PMID 39912983, 2025). "By upregulating PTEN, TUSC8 curtails pathways essential for cancer cell invasiveness, supporting a role that complements both MEG3 and PTENP1 in modulating the tumor microenvironment." (PMID 40242248, 2025). "Overexpressing MEG3 inhibits HCC cell metastasis and angiogenesis induced by M2 polarization, and it suppresses tumor growth in vivo." (PMID 40352941, 2025). "Various lnRNAs exhibited differential expression in tumor suppressive lncRNAs expression were downregulated such as CASC2, GAS5, MEG3, FER1L4, and LINC00672 expression were in EC tissues in contrast to normal tissues." (PMID 39912983, 2025). "MEG3 also inhibited IL4/13 stimulated M2 polarisation as upregulation of MEG3 expression in M2-Bone Marrow-Derived Macrophages (M2-BMDMs) downregulated M2 markers like CD206, YM1, MRC and ARG1, ameliorating tumour proliferation in macrophage-Huh7 co-culture." (PMID 40176927, 2024). "Results showed that miR-330 was significantly upregulated (P < 0.05), whereas MEG3 (P < 0.05) and CNN1 (P < 0.01) were significantly downregulated in tumor tissues compared to paratumor tissue at the RNA level." (PMID 38240701, 2024). "The qPCR analysis was performed to examine the expression levels of MEG3, miR-330, and CNN1 in tumor tissues and cells." (PMID 38240701, 2024). "Among the most proven tumor suppressor lncRNAs are MAGI2-AS3 and MEG3, which suppress OC cell proliferation and invasion or angiogenesis." (PMID 39519394, 2024). "Therefore, MEG3 may exert a tumor suppressor effect through other pathways." (PMID 38334963, 2024). "In CCA cells, low levels of MEG3 correlated with increased proliferation, invasion, and EMT, whereas MEG3 overexpression resulted in reduced tumor cell growth in vitro and in vivo." (PMID 39766138, 2024).
tumor (continued). "Apart from MEG3, MALAT-1 has also been extensively studied in different cancers, highlighting its role in tumor development and progression." (PMID 39448589, 2024). "Furthermore, studies have shown that lower levels of MEG3 expression are associated with a higher WHO grade of tumour, older age at the time of diagnosis, low Karnofsky performance score (KPS), the presence of the wild‐type isocitrate dehydrogenase (IDH), tumour recurrence and poor overall survival." (PMID 37525401, 2023). "Next, immunohistochemistry assay suggested that niraparib treatment intensified MEG3 and GATA6 expression and decreased miR-181-5p expression in tumor tissues, while MEG3 silencing abolished these effects." (PMID 38047026, 2023). "Besides, MEG3 silencing could abrogate niraparib-mediated tumor growth inhibition in mice." (PMID 38047026, 2023). "The expression of tumor suppressor LncRNAs including GAS-5 and MEG3 was significantly augmented in bharangin-treated cells, while this diterpenoid down-regulated oncogenic H19 LncRNA." (PMID 36770654, 2023). "Mir-96 was sponged by MEG3 and led to the increased expression level of TPM, thus inhibiting tumour progression in vivo and in vitro." (PMID 36831352, 2023). "In contrast, other lncRNAs such as the growth arrest-specific transcript 5 (GAS5), the maternally expressed gene 3 (MEG3), and the NF-kB interacting lncRNA (NKILA) function as tumor suppressors, inhibiting proliferation and tumor growth when up-regulated." (PMID 36827545, 2023). "Maternally expressed 3 (MEG3), another tumor-inhibiting factor, inhibits the sponge miR-9-5p cycle and induces gene silencing." (PMID 37021836, 2023). "The lncRNAs interaction with PDCDs is mainly assessed in the context of neoplasia indicating the role of MALAT1, MEG3, SNHG14 and LINC00473 in this process." (PMID 35402235, 2022). "The qPCR analysis performed to ascertain the expression of MEG3 in HNSCC and normal tissue at the vicinity of tumor revealed the interactions between MEG3 and miR-421, E-cadherin and miR-421." (PMID 36530526, 2022). "Among them, FAM30A, HCP5, LINC00963, TMEM147-AS1, and TTTY15 indicated a worse prognosis, but LINC00342, MEG3, HCG18, and N4BP2L2-IT2 demonstrated a better tumor prognosis." (PMID 35615374, 2022). "MEG3 knockdown suppresses the activation effect of DDP on NLRP3/caspase-1/GSDMD pathway-mediated pyroptosis and alters the inhibitory effect of DDP on tumour proliferation and metastasis in triple-negative breast cancer." (PMID 35778526, 2022). "In meningioma, MEG3 accelerates tumor suppressor RB1 directly or indirectly by activating CDKN4A, resulting in tumor cell growth arrest." (PMID 35954272, 2022). "A recent study pointed out that overexpression of MEG3 induced G0/G1 phase arrest by downregulating cyclin D1 expression in PC3 and DU145 cells, thus inducing tumor cell apoptosis in PCa." (PMID 36544907, 2022). "Tumor clusters 1, 2, and 3 were characterized by high expression of the known HB tumor markers REG3A, MEG3 and IGF28." (PMID 36008377, 2022). "According to another research group, the expression level of MEG3 was negatively related to the expression of PI3K, which was closely related to tumor size, metastasis, and vascular infiltration." (PMID 36544907, 2022). "On the other hand, LINC01111, LINC01963, DGCR5, MEG3, GAS5, and LINC00261 are among tumor suppressor lncRNAs in this tissue." (PMID 34827663, 2021). "Our final panel consisted of seven up‐regulated DElncRNAs (CCAT1, CCAT2, H19, HOTAIR, HULC, MALAT1, PCAT1), which were also known as oncolncRNAs and three down‐regulated lncRNAs (MEG3, PTENP1, and TUSC7) as tumor suppressor lncRNAs (tslncRNAs)." (PMID 33094859, 2021). "MEG3 inhibits cell proliferation and metastasis by regulating the expression of miR-5195-3p and FOXO1 in HCC cells, and inhibits tumor growth in vivo." (PMID 34895065, 2021).